VEPH1 (ventricular zone expressed PH domain containing 1)
Description:
Interacts with TGF-beta receptor type-1 (TGFBR1) and inhibits dissociation of activated SMAD2 from TGFBR1, impeding its nuclear accumulation and resulting in impaired TGF-beta signaling. May also affect FOXO, Hippo and Wnt signaling.
Synonyms: KIAA1692; VEPH; FLJ12604; MELT
Tractability: Antibody: UniProt places it where antibodies can reach, with high confidence; its Gene Ontology location is reachable by antibodies, with medium confidence.
Gene: Protein-coding gene on chromosome 3 (157,259,742 to 157,533,619, reverse strand). Ensembl gene ENSG00000197415.
Subcellular location: Cell membrane
Subcellular location (Human Protein Atlas): Cytosol; Nucleoli; Nucleoplasm
Gene Ontology:
Molecular function: protein binding; phosphatidylinositol-5-phosphate binding
Biological process: negative regulation of SMAD protein signal transduction; negative regulation of transforming growth factor beta receptor signaling pathway; regulation of signal transduction
Cellular component: plasma membrane
Genetic constraint (gnomAD): Loss-of-function variants: 78 observed, 88.17 expected, observed/expected ratio (o/e) 0.88, 90% interval 0.74 to 1.07. The synonymous counts are far from expectation, so gnomAD's model fits this gene poorly and the ratio says little. Missense variants: 952 observed, 1,026 expected, observed/expected ratio (o/e) 0.93, 90% interval 0.88 to 0.98. Synonymous variants: 297 observed, 367 expected, observed/expected ratio (o/e) 0.81, 90% interval 0.74 to 0.89.
Homologues: Orthologues: chimpanzee VEPH1 (99% identical), macaque VEPH1 (97% identical), rabbit VEPH1 (90% identical), pig VEPH1 (90% identical), rat Veph1 (86% identical), mouse Veph1 (85% identical), guinea pig VEPH1 (81% identical), dog VEPH1 (79% identical), tropical clawed frog veph1 (63% identical), zebrafish veph1 (58% identical), Drosophila melanogaster melt (17% identical), Caenorhabditis elegans K10B4.3 (14% identical).
Diseases named in the same sentence as VEPH1 in open-access papers:
VEPH1 is named in the same sentence as 22 diseases in open-access papers, as found by Europe PMC text mining. Sharing a sentence is not in itself a finding about the gene and the disease. The quoted sentences say what the papers report.
diabetes (2 papers, 2019 to 2022). "The functional significance of the differential expression of VEPH1 in diabetes, particularly gestational diabetes, warrants further investigation." (PMID 31500637, 2019). "The role of the VEPH1 gene in the development of diabetes has not yet been studied, but Melted, an ortholog of VEPH1 in Drosophila, is known to be involved in insulin/PI3K signaling." (PMID 35885959, 2022).
glioma (2 papers, 2024). A benign or malignant brain and spinal cord tumor that arises from glial cells (astrocytes, oligodendrocytes, ependymal cells). "The identification of MYBL2, RBM6, VEPH1, AHNAK2, GNG10, and DUSP14 as key genes offers valuable insights into the molecular mechanisms underpinning glioma progression and its interaction with COVID-19." (PMID 39684661, 2024). "RBM6 and VEPH1 presented higher expression in primary gliomas, with RBM6 p = 2.0 × 10−9 and VEPH1 p = 8.2 × 10−5, indicating a significant potential protective role." (PMID 39684661, 2024).
melanoma (2 papers, 2022 to 2023). A malignant, usually aggressive tumor composed of atypical, neoplastic melanocytes. "The opposite effects of TGF-β in melanoma is associated with the deregulation of cytokines (TNF-α, VEPH1, SMAD4, INF-γ, SKI) and signaling pathways (Notch1, IL-6, and Erk/MAPK pathway), which in return regulate TGF-β signaling." (PMID 35461253, 2022). "Subsequently, we conducted a joint analysis of proteomic data and TCGA human melanoma RNA-seq data, and found that the mRNA and protein levels of 34 genes, including DSE, VEPH1, SFRP4, TTN, STSE, were consistently down-regulated in melanoma tissues." (PMID 37833287, 2023). "The poorly expressed ventricular zone expressed PH domain-containing 1 (VEPH1) and up-regulated upstream transcription factor 1 (USF1) in melanoma tissues promoted EMT." (PMID 35461253, 2022).
osteosarcoma (2 papers, 2019 to 2021). A usually aggressive malignant bone-forming mesenchymal neoplasm, predominantly affecting adolescents and young adults. "A study with osteosarcoma cells also shows decreased VEPH1 expression associated with a known driver of disease progression." (PMID 31500637, 2019). "VEPH1 expression was decreased in osteosarcoma, and it inhibited the viability, proliferation, and migration of osteosarcoma cells." (PMID 34903122, 2021). "miR-23b-3p targets VEPH1 and promotes osteosarcoma via PI3K/AKT pathway." (PMID 34903122, 2021). "Overexpression of COX2 in U2OS osteosarcoma cells resulted in down-regulation of 20 genes, including VEPH1, suggesting that VEPH1 may be a negative regulator of osteosarcoma cell proliferation or invasion by up-regulated COX2 expression." (PMID 31500637, 2019).
ovarian carcinoma (2 papers, 2019 to 2021). A malignant neoplasm originating from the surface ovarian epithelium. "Consistent with this prediction, expression of VEPH1 in SKOV3 ovarian cancer cells is associated with decreased levels of AKT." (PMID 31500637, 2019). "Amplification of the VEPH1 gene locus associated with increased transcript levels has been reported in ovarian cancers, and query of the TCGA database indicates potential amplification in multiple other cancers." (PMID 31500637, 2019). "Numerous studies have demonstrated that VEPH1 expression is altered in cancers such as hepatocellular carcinoma, ovarian cancer, colon cancer, lung cancer, and prostate cancer." (PMID 34903122, 2021). "We have confirmed VEPH1 protein expression in some human ovarian cancer cell lines by western blot analysis." (PMID 31500637, 2019). "For example, most of the VEPH1 expressed by ES2 ovarian cancer cells is in an unphosphorylated state, whereas that expressed by PC-3 prostate cancer cells and HEC1B endometrial cancer cells is hyperphosphorylated." (PMID 31500637, 2019). "Consistent with the impact of Drosophila melted on signaling pathways, expression of VEPH1 cDNA in ovarian cancer SKOV3 cells was shown to affect FoxO, mTOR, and YAP/TAZ signaling networks by pathway analysis of differentially expressed genes identified by microarray-based gene expression profiling." (PMID 31500637, 2019). "In an initial test of this, we found that VEPH1 expression in an ovarian cancer cell line did not impact the ability of these cells to form tumors but slowed tumor progression relative to those formed by mock-transfected cells." (PMID 31500637, 2019).
alcoholism (1 paper, 2017). "While many identified genes were generally in alignment with prior knowledge, further work should be done to understand the associations between alcoholism and the five genes that went uncorroborated in the literature (BLNK, BMPER, PDLIM5, VEPH1, AMPD3)." (PMID 28361705, 2017).
chordoma (1 paper, 2019). Chordomas are rare malignant tumors arising from embryonic remnants of the notochord in axial skeleton. "Given the central role of Brachyury in chordoma, this finding raises the possibility that VEPH1 may promote this cancer." (PMID 31500637, 2019). "Increased VEPH1 expression is driven by Brachyury/TBXT, a T-box transcription factor highly expressed in chordoma, a rare cancer derived from notochord remnants." (PMID 31500637, 2019).
COVID-19 (1 paper, 2024). A disease caused by infection with severe acute respiratory syndrome coronavirus 2. "Given the protective associations observed with RBM6 and VEPH1 expression, vitamin D may enhance their beneficial effects, offering a synergistic approach to improve patient outcomes amidst the challenges posed by COVID-19." (PMID 39684661, 2024).
dysplasia (1 paper, 2019). A usually neoplastic transformation of the cell, associated with altered architectural tissue patterns. "Identification of interacting partners of VEPH1 responsible for neural dysplasia in model organisms: In contrast to the mouse model, disruption of VEPH1 in non-mammalian model organisms compromised neural development." (PMID 31500637, 2019).
endometrial cancer (1 paper, 2019). Primary or metastatic malignant neoplasm involving the endometrium (mucous membrane that lines the endometrial cavity). "In addition, endogenous VEPH1 protein expression is detectable in HEC1B endometrial cancer cells, PC-3 prostate cancer cells, CRL2854 prostate stromal cells, T47D breast cancer cells, and human umbilical vein endothelial cells (HUVEC)." (PMID 31500637, 2019).
gastric cancer (1 paper, 2019). A primary or metastatic malignant neoplasm involving the stomach. "However, in gastric cancer, VEPH1 expression is decreased by > 50% in early stage disease, suggesting loss of VEPH1 expression may enable malignant transformation or survival of these cells." (PMID 31500637, 2019).
kidney cancer (1 paper, 2024). Primary or metastatic malignant neoplasm involving the kidney. "Several genes showed a low gDS in most kidney cancer cell lines, such as CD82, CD7, MEST, SELP, BMP6, CA2, DNAJC6, and VEPH1." (PMID 38728235, 2024).
liver cancer (1 paper, 2024). An epithelial or non-epithelial malignant neoplasm that arises from the liver. "However, WWP1 ubiquitinates and degrades KLF14, which lacks a PY motif, suppressing VEPH1 expression and promoting liver cancer cell proliferation, invasion, and migration." (PMID 39949609, 2024). "In liver cancer tissues, KLF14 expression is significantly downregulated, yet it accumulates at the VEPH1 promoter, enhancing VEPH1 transcription and protein expression." (PMID 39949609, 2024).
prostate carcinoma (1 paper, 2019). A carcinoma that arises from epithelial cells of the prostate gland. "In contrast, VEPH1 expression is decreased by STK4/MST1 overexpression in prostate cancer cell lines." (PMID 31500637, 2019). "Altogether these studies raise the possibility that VEPH1 may augment signaling networks involved in prostate cancer progression and may be involved in mesenchymal-epithelial cell transitions that can impede metastasis while promoting expansion of lesions formed by metastatic cells." (PMID 31500637, 2019).
pulmonary fibrosis (1 paper, 2019). Chronic progressive interstitial lung disorder characterized by the replacement of the lung tissue by connective tissue, leading to progressive dyspnea, respiratory failure, or right heart failure. "VEPH1 is decreased in idiopathic human pulmonary fibrosis and is similarly decreased in bleomycin-induced pulmonary fibrosis in a rat model." (PMID 31500637, 2019).
sarcoma (1 paper, 2019). A usually aggressive malignant neoplasm of the soft tissue or bone. "Among cell lines queried for VEPH1 transcripts, several endothelial, neural, fibroblast, breast, and sarcoma cell lines have been shown to express VEPH1 transcripts (human protein atlas)." (PMID 31500637, 2019).
cancer (4 papers, 2019 to 2022). A tumor composed of atypical neoplastic, often pleomorphic cells that invade other tissues. "Some researchers have found that VEPH1 is frequently decreased in cancer, an event associated with poor prognosis of cancer patients." (PMID 35935338, 2022). "A growing list of studies show altered expression levels of VEPH1 associated with various disease states, with studies in cancer indicating potential pro- and anti-tumorigenic activities." (PMID 31500637, 2019). "Proteomic investigations have identified VEPH1 as a component of exosomes originating from various cell types including trophoblast cells, cancer associated fibroblasts, and mesenchymal stem cells." (PMID 31500637, 2019). "Loss of VEPH1 decreases TSC2 GAP activity, and relieves Rheb to activate mTORC1, which promotes cancer cell proliferation, invasion, and EMT process." (PMID 35935338, 2022). "Although considerable evidence exits for the differential expression of VEPH1 in different types of cancers, the function and mechanism of VEPH1 in OS are rarely studied and discussed." (PMID 34903122, 2021). "In summary, this study preliminarily demonstrated that miR-23b-3p, as a cancer promoter, interacted with VEPH1/PI3K/AKT in OS and facilitated the malignant phenotypes of OS cells." (PMID 34903122, 2021). "Levels of VEPH1 have been shown to be affected by expression of various drivers of cancer progression." (PMID 31500637, 2019). "Much of what is known about the function of this protein is inferred from studies of its ortholog in Drosophila; however, expression of VEPH1 is altered in several pathological conditions, including metabolic and neurologic conditions, and cancer." (PMID 31500637, 2019). "Tumorigenesis and vascularization: The impact of VEPH1 on multiple cell signaling pathways implicated in tumor initiation and progression, together with reports of altered VEPH1 expression in multiple cancers indicates a potential role in tumor progression." (PMID 31500637, 2019). "Other researchers have reported that VEPH1 is abnormally expressed in a variety of cancers." (PMID 34903122, 2021). "Some studies offer support for the idea that VEPH1 may be involved in cancer initiating events." (PMID 31500637, 2019). "Thus, the potential impact of VEPH1 on cancer progression may be altered in the context of nuclear β-catenin levels." (PMID 31500637, 2019). "Several other genes in our model have been independently verified as oncogenes (SPAG5, PARM1) or tumor suppressors (VEPH1, GLCE) in prostate or other cancers, showcasing the ability of our TET2-based model to capture these key changes." (PMID 33008340, 2020). "Of these genes, VEPH1 along with MCM5, PINK1, and SLC2A1 genes provided the best discriminatory power, with VEPH1 expression decreased by 90% in the aggressive cancers (cluster 1) compared to those with better survival." (PMID 31500637, 2019). "Previous studies have reported that VEPH1 is an intracellular adaptor protein that regulates signaling pathways such as mTOR, TGF-β, AKT, Wnt, FoxO, and Hippo, thus affecting the progression of pathological processes, including cancers." (PMID 34903122, 2021). "Similarly, we found lower VEPH1 expression in a range of OS cells (U2OS, SJSA-1, HOS, and Saos-2) than in the non-cancer cell line (hFOB1.19)." (PMID 34903122, 2021). "Studies in mammals indicate a role for VEPH1 in modulating TGFβ signaling and AKT activation, while numerous studies indicate VEPH1 expression is altered in several pathological conditions, including cancer." (PMID 31500637, 2019).
tumor (3 papers, 2019 to 2021). "Consistent findings were obtained in this study, in which VEPH1 was found to be downregulated in OS tissues as well as cells and VEPH1 acted as a tumor suppressor in OS cells." (PMID 34903122, 2021). "It has been reported that VEPH1, as an endogenous regulatory protein, regulates multiple signaling pathways, thereby affecting tumor progression." (PMID 34903122, 2021). "VEPH1 transcripts were also found to be decreased in lung squamous cell carcinoma relative to non-tumour lung tissue in microarray studies performed on either macro-dissected and laser-capture micro-dissected tissues." (PMID 31500637, 2019). "Further work is needed to define the impact of VEPH1 expression on tumor progression, including tumor expansion, angiogenesis, and metastasis using orthotopic syngeneic models." (PMID 31500637, 2019). "Overall, these findings revealed that VEPH1 is a tumor suppressor gene, whose expression is suppressed by miR-23b-3p in OS and that VEPH1 could partially attenuate the promoting function of miR-23b-3p in OS cell viability, proliferation, and migration." (PMID 34903122, 2021). "Somewhat surprisingly, VEPH1 expression did not appear to alter tumor cell proliferation but rather increased necrotic regions within the tumor." (PMID 31500637, 2019).
VEPH1 also shares sentences with these, for which no sentence is quoted: abdominal aortic aneurysm (1 paper); atherosclerosis (1); breast carcinoma (1); invasive breast carcinoma (1).